TAP1 (transporter 1, ATP binding cassette subfamily B member)
Description:
ABC transporter associated with antigen processing. In complex with TAP2 mediates unidirectional translocation of peptide antigens from cytosol to endoplasmic reticulum (ER) for loading onto MHC class I (MHCI) molecules. Uses the chemical energy of ATP to export peptides against the concentration gradient. During the transport cycle alternates between 'inward-facing' state with peptide binding site facing the cytosol to 'outward-facing' state with peptide binding site facing the ER lumen. Peptide antigen binding to ATP-loaded TAP1-TAP2 induces a switch to hydrolysis-competent 'outward-facing' conformation ready for peptide loading onto nascent MHCI molecules. Subsequently ATP hydrolysis resets the transporter to the 'inward facing' state for a new cycle. Typically transports intracellular peptide antigens of 8 to 13 amino acids that arise from cytosolic proteolysis via IFNG-induced immunoproteasome. Binds peptides with free N- and C-termini, the first three and the C-terminal residues being critical. Preferentially selects peptides having a highly hydrophobic residue at position 3 and hydrophobic or charged residues at the C-terminal anchor. Proline at position 2 has the most destabilizing effect. As a component of the peptide loading complex (PLC), acts as a molecular scaffold essential for peptide-MHCI assembly and antigen presentation.
Synonyms: APT1; PSF-1; RING4; ABCB2; PSF1; D6S114E; ABC17; MHC1D1; TAP1*0102N; TAP1N
Tractability: Small molecule: a structure with a bound ligand is known. Antibody: UniProt predicts a signal peptide or a membrane-spanning region. PROTAC: ubiquitination databases record sites on it; its protein half-life has been measured.
Gene: Protein-coding gene on chromosome 6 (32,845,206 to 32,854,018, reverse strand). Ensembl gene ENSG00000168394.
Subcellular location: Endoplasmic reticulum membrane
Subcellular location (Human Protein Atlas): Centriolar satellite; Endoplasmic reticulum
Pathways (Reactome):
Immune System: Antigen Presentation: Folding, assembly and peptide loading of class I MHC; ER-Phagosome pathway
Gene Ontology:
Molecular function: ABC-type peptide antigen transporter activity; ADP binding; ATP binding; MHC class Ib protein binding; peptide antigen binding; peptide transmembrane transporter activity; protein binding; TAP2 binding; protein homodimerization activity; TAP1 binding; ABC-type peptide transporter activity; ABC-type transporter activity; ATP hydrolysis activity; MHC class I protein binding; MHC protein binding
Biological process: antigen processing and presentation of endogenous peptide antigen via MHC class I; cytosol to endoplasmic reticulum transport; peptide transport; adaptive immune response; defense response; transmembrane transport
Cellular component: endoplasmic reticulum; endoplasmic reticulum membrane; membrane; MHC class I peptide loading complex; TAP complex; endoplasmic reticulum-Golgi intermediate compartment membrane; phagocytic vesicle membrane; cytoplasm
Genetic constraint (gnomAD): Loss-of-function variants: 56 observed, 79.89 expected, observed/expected ratio (o/e) 0.7, 90% interval 0.56 to 0.88. The upper end of that interval is the gene's LOEUF score, 0.88, which puts it in group 3 of 6, group 1 being the genes least tolerant of losing a copy. Missense variants: 737 observed, 965.63 expected, observed/expected ratio (o/e) 0.76, 90% interval 0.72 to 0.81. Synonymous variants: 355 observed, 416.28 expected, observed/expected ratio (o/e) 0.85, 90% interval 0.78 to 0.93.
Gene-disease validity (ClinGen):
ClinGen rates the evidence that TAP1 causes each of these diseases.
MHC class I deficiency (autosomal recessive): Definitive.
Homologues: Orthologues: chimpanzee TAP1 (99% identical), macaque PSMB8 (89% identical), pig TAP1 (81% identical), rabbit TAP1 (79% identical), dog TAP1 (78% identical), guinea pig TAP1 (70% identical), mouse Tap1 (70% identical), rat Tap1 (70% identical), tropical clawed frog tap1 (44% identical), zebrafish tap1 (44% identical), tropical clawed frog tap1 (30% identical), Caenorhabditis elegans haf-7 (27% identical), and 8 more. Paralogues in human: ABCB9 (35% identical), TAP2 (35% identical), ABCB10 (28% identical), ABCB1 (28% identical), ABCB4 (27% identical), ABCB8 (26% identical), ABCB5 (25% identical), ABCB11 (25% identical), ABCB6 (21% identical), ABCB7 (21% identical).
Diseases named in the same sentence as TAP1 in open-access papers:
TAP1 is named in the same sentence as 173 diseases in open-access papers, as found by Europe PMC text mining. Sharing a sentence is not in itself a finding about the gene and the disease. The quoted sentences say what the papers report.
melanoma (34 papers, 2010 to 2025). A malignant, usually aggressive tumor composed of atypical, neoplastic melanocytes. "In colorectal cancer, cervical cancer, melanoma, and esophageal cancer, the loss of TAP1 expression ranges from 10% to 80.4%, and the loss of TAP1 expression suggests poor prognosis in tumor patients." (PMID 39820491, 2025). "Low TAP1 expression correlates with tumor progression, loss of regression and increased development of melanoma metastases." (PMID 26735690, 2016). "B16 melanoma cells are poorly immunogenic due to downregulation of transporters associated with antigen processing (TAP-1 and TAP-2), resulting in reduced MHC class I expression and a diminished ability to present antigens to CD8+ T cells." (PMID 23768240, 2013). "Loss of TAP1 expression in melanoma was correlated with the increase of Treg cells and neutrophils in cancer, which could change the immune microenvironment and participate in the reversal of resistance to anti-PD1 therapy." (PMID 34957213, 2021). "Furthermore, an inverse expression of miR-26b-5p and miR-21-3p with TAP1 was found in primary melanoma lesions, which was linked with the frequency of CD8+ T cell infiltration." (PMID 32825219, 2020). "In previous work, downregulation of TAP1 protein expression could be observed in primary melanoma lesions that is associated with significant higher invasive melanoma growth and a lack of tumor-infiltrating lymphocytes." (PMID 26735690, 2016). "In the present study, immunofluorescence images of melanoma and normal epithelial cells revealed that TAP1 was strictly distributed on the ER." (PMID 36759763, 2023). "MHC-I, TAP1 and B2M expression were found to be up-regulated after treatment of melanoma cells with BO-112, an activator of dsRNA sensing and NF-κB signalling, restoring the cytotoxic activity of tumour-specific T cells." (PMID 35343573, 2022). "It is found that TAP1, antigen processing 1, is correlated with good prognosis in colorectal cancer and melanoma patients." (PMID 35725413, 2022). "Here, we show that ACB1801 upregulates the mRNA expression of several proteins of the MHC-I such as Transporter Associated with antigen Processing TAP1 and 2, Tapasin and Lmp2 (hereafter referred to as MHC-I signature) in melanoma cells." (PMID 36458012, 2022). "At the end of 3-week mavorixafor monotherapy, expression scores for a panel of antigen processing and presentation genes measured in melanoma biopsies, which included B2M, TAP1/TAP2, and multiple HLA complex genes, trended toward an increase." (PMID 36923305, 2022). "miR-200a-5p overexpressed in melanoma cells increases their sensitivity to being killed by NK cells by directly targeting TAP1, followed by the reduced expression of HLA-I." (PMID 34827646, 2021). "Higher TAP1 (a), HLA-A (b), HLA-B (c) and HLA-C (d) mRNA transcript levels correlated with an increased OS of melanoma patients." (PMID 32825219, 2020). "The miR-mediated downregulation of TAP1 was accompanied by decreased HLA class I surface antigen expression, but to a different extent among the melanoma cell lines." (PMID 32825219, 2020). "Using this model, a clear correlation of exogenously administered IFNα on the proliferative potential of transplanted B16 melanomas and enhanced TAP1 expression in peripheral blood and tumor tissue was demonstrated." (PMID 26735690, 2016). "IFNα treatment led to an upregulation of TAP1 expression in PBMCs of patients with malignant melanoma." (PMID 26735690, 2016). "IFNα also induced expression of TAP1 in mouse blood and tumor tissue and suppressed the formation of melanoma metastasis in an in vivo B16 tumor model." (PMID 26735690, 2016). "To gain more insight into the biological effects of IFNα on TAP1 regulation, we investigated the in vivo anti-tumor activity of this molecule against murine melanoma cells using the murine C57BL/6-B16F1 tumor transplantation model." (PMID 26735690, 2016).
melanoma (continued). "In this study, we showed that adjuvant IFNα therapy clearly increases TAP1 expression in PBMCs of stage III melanoma patients." (PMID 26735690, 2016). "To date, different groups investigated the impact of TAP1 on MHC I antigen presentation in tumor cells and addressed TAP1 downregulation in melanoma as a tumor-specific immune escape mechanism." (PMID 26735690, 2016). "It was shown that transfection or adenoviral inoculation of TAP1 in melanoma cells increase tumor-specific immune response in vitro and in vivo and restore immune surveillance against melanoma." (PMID 26735690, 2016). "In summary, a correlation was observed between an enhanced TAP1 mRNA expression in peripheral blood and tumor tissue and the suppressed formation of subcutaneous melanoma metastasis in animals receiving adjuvant IFNα therapy." (PMID 26735690, 2016). "To study the mechanisms of action of IFNα-2b (IntronA) in adjuvant immunotherapy of metastatic melanoma we investigated the expression of TAP1 in peripheral blood mononuclear cells (PBMCs) of 18 patients diagnosed with UICC stage III malignant melanoma." (PMID 26735690, 2016). "In previous studies, gene promoter hypermethylation was associated with downregulation of tapasin, TAP1, TAP2, and LMP7 protein expression in esophageal squamous cell carcinoma, colon cancer, renal cancer, and melanoma." (PMID 23024775, 2012). "Moreover, high MHC-I expression has been proposed as a predictor of ICB response, and high expression of MHC-I and other APP genes, including NLRC5 and TAP1, correlates with better survival in patients with melanoma, for whom ICB is a first-line therapy." (PMID 38973593, 2024). "Interestingly, HLA-class I APM component levels (Delta, LMP-7/10, TAP-1, Calnexin, Tapasin, β2-microglobulin, and HLA-A,B,C) were lower in immature epidermal LCs compared to melanoma-positive SLN LCs, and significantly increased after LCs maturation." (PMID 38791968, 2024). "Moreover, high MHC-I expression has been proposed as a predictor of ICB response 28–31, and high expression of MHC-I and other APP genes, including NLRC5 and TAP1, correlates with better survival in patients with melanoma, for whom ICB is a first-line therapy." (PMID 37066260, 2024). "Importantly, TAP1 and HLA-A are essential components of T cell function, and high expression of these molecules was found to increase the survival probability of melanoma patients." (PMID 37175874, 2023). "The therapeutic value of ACB1801-dependent increase of TAP1, TAP2, Tapasin and Lmp2 is underscored by clinical data showing that high expression levels of these proteins was observed in melanoma patients that respond to anti-PD-1 and associated with an improved survival of melanoma patients." (PMID 36458012, 2022). "High expression of TAP1 and HLA-A increased the survival probability of melanoma patients." (PMID 34827646, 2021). "Moreover, the overexpression of miR-21-3p or miR-26b-5p resulted in a reduced TAP1 protein expression in melanoma cells." (PMID 32825219, 2020). "MiR-21-3p was strongly enriched in miTRAP eluates of TAP1 and proved to directly bind to the 3′ UTR, thereby decreasing TAP1 protein expression, which supported its reported oncogenic role in melanoma, similar to what has been described in other types of cancers." (PMID 32825219, 2020). "Overexpression of miR-26b-5p and miR-21-3p in melanoma cells downregulated the TAP1 protein and reduced expression of HLA class I cell surface antigens, which could be reverted by miR inhibitors." (PMID 32825219, 2020). "After demonstrating the stimulatory effect of IFNα on expression of TAP1 in primary human monocytic cells, murine blood cells and melanoma tissue we investigated the effect of IFNα on the expression of TAP1 in vitro in monocytic THP1 cells and the melanoma cell line A375." (PMID 26735690, 2016).
melanoma (continued). "We could show that IFNα upregulates TAP1 expression in peripheral blood mononuclear cells (PBMCs) of patients with malignant melanoma receiving adjuvant high-dose immunotherapy." (PMID 26735690, 2016). "Furthermore, clinical investigations showed that reduced expression of TAP1 represents an independent prognostic marker for melanoma." (PMID 26735690, 2016). "Here, we report that, in B16-F10 melanoma cells, ACB1801 upregulates the expression of proteins involved in the MHC-I peptide-loading complex, such as transporter associated with antigen processing proteins 1 and 2 (TAP1 and TAP1), Tapasin and low-molecular-weight proteins 2 (Lmp2)." (PMID 36458012, 2022). "Indeed, low TAP1 expression or loss of TAP transporter function in melanoma allows evasion from immune surveillance through a lack of tumor antigen presentation." (PMID 26735690, 2016). "Upregulations of Cxcl9, Cxcl10, Cxcl11, Ccl5, Tap1, CD74, Irf1, Icam1, CD40, Fas and PD-L1 were detected after Mi-2β silencing and the anti-PD-1 treatment in BRafV600E/Ptennull melanomas." (PMID 38461299, 2024). "Next, we obtained multiple human malignant melanoma and colon adenocarcinoma tissue samples and stained for 5hmC as a marker for TET2 activity and for the key MHC I antigen-presenting genes TAP1, TAPBP, and B2M." (PMID 39388288, 2024). "Here, we show that TET2 in B16-OVA melanoma tumor cells is important for expression of some MHC class I antigen presentation genes, including the key regulators TAP1 and TAPBP, which are regulated downstream of IFN-γ–induced signaling." (PMID 39388288, 2024). "Expression of TAP1, TAPBP, and B2M was higher in 5hmC-high melanoma samples than 5hmC-low samples, indicating a positive correlation between TET2 activity and MHC I antigen-presenting genes." (PMID 39388288, 2024). "In previous studies, patients with primary or metastatic urothelial cancer, breast cancer, and melanoma were treated with single or combined monoclonal antibodies against PD-L1, PD-1, and CTLA-4, and the clinical outcomes suggest a protective role for TAP1." (PMID 36759763, 2023). "We assessed the impact of ACB1801 on the expression of antigen presentation genes (TAP1, TAP2, Tapasin, b2m, Lmp2, Lmp10, PA28α and PA26β) in murine B16-F10 melanoma." (PMID 36458012, 2022). "Collectively, these data highlight the therapeutic value of increasing the expression levels of TAP1, TAP2, TAPBP and PSMB9 in melanoma." (PMID 36458012, 2022). "Using melanoma B16 cells, the authors demonstrate that the HDACi, TSA increases the expression of several components of the antigen processing machinery, including TAP-1, TAP-2, LMP-2, and Tapasin." (PMID 32500025, 2020). "Since the immune cell infiltration of the same melanoma samples was previously analyzed for the presence of CD8+ T cells by immunohistochemistry (IHC), it was possible to correlate TAP1 and miR expression to CD8 infiltration." (PMID 32825219, 2020). "The TAP1 expression scores were directly correlated with the frequency of CD8+ immune cells, with TAP1low and TAP1high melanoma lesions exhibiting the low and high frequency of CD8+ T cells respectively." (PMID 32825219, 2020). "To introduce fluorescent TAP-GFP into human melanoma MJS cells, we first generated, by using CRISPR/Cas9-based technology, TAP1 or TAP2 knock-outs (KO)." (PMID 31817841, 2019). "Collectively, these results show that GGTase I inhibition enhances hIFN-γ-induced TAP1 and TAP2 expression in this human melanoma cell line." (PMID 20140259, 2010). "As previously observed in the murine melanoma model, the GGTase I inhibition enhances IFN-γ-induced MHC class I expression through a mechanism involving TAP1 and TAP2 over-expression." (PMID 20140259, 2010). "In the current study we used the LB1319-MEL human melanoma model to investigate the effects of 4 days of in vitro treatment with hIFN-γ (50 IU/mL) and/or GGTI-298 (10 μM) on the expression of TAP1, TAP2, tapasin, PA28, LMP2, LMP7, and LMP10 proteins." (PMID 20140259, 2010).
melanoma (continued). "As was observed for melanoma cells, IFNγ treatment of Ptpn2 knockout CT26 and MC38 cells enhanced the expression of the IFNγ response genes Cxcl1, Ccl5, Stat1, Stat2, Stat3, Irf1, Pd-l1, Tap1, and Casp8, compared with IFNγ-treated control cells." (PMID 36968224, 2023). "Furthermore, the overexpression of TAP1, as a representative protein of the MHC-I, was detected in human melanoma cells A375, and colorectal HCT166 cells as well as in glioblastoma (U87 and U251) cells." (PMID 36458012, 2022). "We showed that melanoma patients who were responsive to anti-PD-1 expressed significantly higher levels of TAP1, TAPASIN, LMP2, but not TAP2, compared to those who were not responsive to this therapy." (PMID 36458012, 2022). "In contrast to our current and previous work, which showed an upregulation of TAP1 in PBMCs of IFNα treated patients, they found no TAP1 regulation in tissue of human melanoma lymph node metastasis after IFNα treatment." (PMID 26735690, 2016). "Methylation of the tapasin and/or TAP2 promoter has been reported in melanoma and RCC cell lines and treatment with DNA demethylation agent 5-aza-2′-deoxycytidine (5-AC) results, not only in the enhancement and/or reconstitution of tapasin and TAP2, but also in TAP1 transcription and translation." (PMID 24212778, 2011). "In both the para-cancerous normal (HaCaT) and melanoma (SKMEL30) cell lines, TAP1 protein was clearly located at the ER, with no change observed before and after tumorigenesis." (PMID 36759763, 2023).